VEGFA (vascular endothelial growth factor A)
Diseases named in the same sentence as VEGFA in open-access papers (continued):
Sharing a sentence is not in itself a finding about the gene and the disease.
tumor (continued). "By tumor-vascular endothelial cell interaction model, we for the first time reported that low-dose ICJ, with little cytotoxic effects, induces the anergy of HUVEC to VEGFA pro-angiogenic signals from tumor and downregulates VEGFR2 in an autophagy dependent manner." (PMID 29403376, 2017). "On the other hand, before tumor arrival in the metastatic sites, the primary tumor also produces systemic factors, for example, VEGFA, TGFβ, TNF, and LOX, which induce chemotactic protein expressions like S100A8, S100A9, SAA3 and extracellular matrix remodeling." (PMID 29450136, 2017). "The present study investigated, by immunohistochemical analysis, the protein expression of HIF-1α, PDK1, PHD3, PFKFB4, and VEGFA, five genes extensively modulated in hypoxic conditions, the typical state of tumor microenvironment strictly connected with cancer cells growth and propagation." (PMID 29117193, 2017). "VEGFA exposure had effects long after VEGFA withdrawal to increase OVCA tumor initiation in vivo; thus, we speculated that VEGFA might regulate miR‐128‐2 epigenetically." (PMID 28179359, 2017). "Furthermore, the expression of VEGFA which over-expressed in the MMQ tumor stem-like cells was detected in tumor spheres isolated from human prolactinomas." (PMID 28163656, 2017). "MiR-29c acts as a tumor suppressor by targeting VEGFA and may represent a promising prognostic biomarker as well as a potential therapeutic target for LAD." (PMID 28241836, 2017). "Furthermore, Fibronectin and VEGFA levels were enhanced in tumor-fibroblast co-cultures in a p38MAPK-dependent manner, as genetic or pharmacological inhibition of p38 reduced Fibronectin levels." (PMID 28977919, 2017). "In particular it has been reported that VEGFA or PLGF released by tumor, through a mechanism dependent on metalloproteinase-9 and soluble Kit ligand, increase the number of these cells in bloodstream, while CXCL12 and CXCR4 receptor favor their retention in perivascular site of injured issues." (PMID 29270405, 2017). "However, in transgenic mice, overexpression of miR-17-92 inhibits tumor growth and tumor angiogenesis by targeting multiple genes, such as transforming growth factor β type II receptor, hypoxia induced factor-1α and vascular endothelial growth factor A." (PMID 29137282, 2017). "VEGFA blockade, by interrupting angiogenesis, creates tumor hypoxia." (PMID 28179359, 2017). "The mRNA and protein levels in HCC tumor cells are significantly higher than those in para-carcinoma tissue (P<0.01), and the overexpression of VEGFA could promote paracrine secretion of hepatocyte growth factor (HGF)." (PMID 28903454, 2017). "VEGFA and Ang-2 are two important regulators of tumor angiogenesis." (PMID 28178668, 2017). "After insufficient RFA, tumor-associated endothelial cells have enhanced angiogenesis and invasiveness of residual HCC, and this may promote tumor angiogenesis via HIF-1α/VEGFA pathway." (PMID 28732507, 2017). "Furthermore, the patients with tumor recurrence showed a significant rise in serum concentrations of VEGFA." (PMID 28163656, 2017). "Our observations led to the hypothesis that VEGFA amplification may suppress the attraction of macrophages and lymphocytes towards the tumor front." (PMID 28403223, 2017). "In addition to being produced by a substantial proportion of tumors and being over-expressed when amplified, VEGFA is also secreted by various cell types, including macrophages and lymphocytes, in the tumor microenvironment." (PMID 28403223, 2017). "PDGFB and VEGFA were angiogenic factors and mediated tumor growth, angiogenesis and metastasis." (PMID 27833078, 2016). "PCa cells also express factors such as TGFβ (transforming growth factor beta), WNT family members such as Wnt5a and the pro-angiogenic factor VEGFA that promote an aggressive tumor phenotype and bone metastases by directly affecting osteoclast and osteoblast formation." (PMID 27776343, 2016).
tumor (continued). "Also, metronomic TPT treatment led to a decreased VEGFA expression and reduced tumor vascularization." (PMID 26657295, 2016). "It should be noted that other Nrp1-mediated pathways, particularly VEGFA, semaphorin 3A, and HGF signaling may also play important roles in the overall modalities of how GAMs associate with the tumor microenvironment." (PMID 26755653, 2016). "Tumor cells produce VEGFA protein to promote the development of vasculature, providing a sufficient supply of oxygen and nutrients, suggesting that VEGFA could be a potential target for cancer therapy." (PMID 27777493, 2016). "Blocking VEGFA-induced disassembly of endothelial junctions, thereby suppressing tumour oedema and metastatic spread, may be preferable to full vascular suppression in the treatment of certain cancer forms." (PMID 27005951, 2016). "In addition, the BET inhibitory treatment leads to a significant reduction of both the global tumor-vascularization as well as the VEGFA expression within the tumor-cells." (PMID 27006472, 2016). "Overexpression of VEGFA has been detected in a number of human tumor tissues." (PMID 27777493, 2016). "Also, tumor angiogenesis can result in a dysfunctional vasculature relied on VEGFA and its effectors." (PMID 26901069, 2016). "Thus, the VEGFA-resistant vessel barrier phenotype in the Vegfr2Y949F/Y949F tumours correlated with an enhanced drug effect at D12, probably due to the lower oedema, and hence a lower interstitial tumour pressure, at this stage." (PMID 27005951, 2016). "Many reports have described the close relationship between tumor and endothelium, as well as documenting the existence of a pool of tumor-derived angiocrine factors that induce vessel development, including vascular endothelial growth factor (VEGFA)." (PMID 27322147, 2016). "TUG1-miR-34a-5p-VEGFA network is involved in tumor angiogenesis." (PMID 27362796, 2016). "Tumor cells secrete elevated levels of various growth factors, and our previous work showed that elevated levels of vascular endothelial growth factor A (VEGF-A) induce centrosome over-duplication in EC." (PMID 27977771, 2016). "VEGFA was upregulated in OS tumor tissues and SAOS-2 and U2OS cell lines." (PMID 27777493, 2016). "The new pattern appears in both cancer cell lines and fresh tumor samples, and may predict the expression levels of important oncogenes across cancers and patients, as demonstrated for the VEGFA gene." (PMID 26886256, 2016). "Despite this relatively diminished vascularity compared to other tumor types, elevated pro‐angiogenic vascular endothelial growth factor A (VEGF‐A) levels in patients have been found to correlate with increased vascular density of PDAC and greater disease progression." (PMID 26747091, 2016). "Interestingly, CCL2 overexpression induces tumor angiogenesis via TAMs, and VEGFA production in regions of hypoxia in growing tumors benefits TAM accumulation." (PMID 27541266, 2016). "It is pertinent to ask whether the reduced metastatic spread in the Vegfr2Y949F/Y949F tumours can be attributed directly to the VEGFA-resistant Y949F junctions, that is, do tumour cells intravasate into the circulation via junctions?" (PMID 27005951, 2016). "Tumor development usually involves a hypoxic state sensed by the mTOR pathway leading to an activation of the hypoxia-inducible factor 1 alpha (HIF1A) to facilitate angiogenesis upon VEGFA induction." (PMID 27090655, 2016). "Furthermore, the level of miR-126 was downregulated in NSCLC compared to noncancerous lung tissues due to the fact that miR-126 participates in tumor angiogenesis by targeting the expression of vascular endothelial growth factor-A." (PMID 27093275, 2016). "We demonstrated that miR-1-mediated downregulation of VEGFA inhibited cell growth, migration, and invasion in OS cells, suggesting that miR-1 might act as a tumor suppressor in OS at least partially through targeting VEGFA." (PMID 27777493, 2016).
tumor (continued). "Consistent with the reduced expression of VEGFA mRNA in siRND3 transfected U87 cells, blood vessel density in siRND3 tumours was significantly lower compared to control tumours (siRND3 oligo B U87 10.6±2.79; control U87 23.8±2.13), suggesting a disrupted angiogenesis process." (PMID 26132659, 2015). "In addition, IHC staining of mouse RCC tumors showed the expressions of ERβ, VEGFa, and HIF2α markers were consistently higher in 786-O+HL-60N tumor group than 786-O tumor group." (PMID 26079540, 2015). "However, ATF4 overexpression failed to increase the expression level of a series of proangiogenic factors including vascular endothelial growth factor A (VEGFA) in tumor cells in this model." (PMID 25883982, 2015). "Angiogenesis is essential during the development of tumor and multiple proangiogenic factors such as vascular endothelial growth factor-A (VEGF-A) and PDGF-B can be induced by MUC1 under hypoxia, which promote the synthesis of new blood vessels within the tumor masses." (PMID 26367866, 2015). "Tumor associated macrophages (TAM) also release MMP-9, and the increase in MMP-9 can result in the release of matrix-sequestered vascular endothelial growth factor-A (VEGF-A)." (PMID 25664615, 2015). "The identified targets of miR-93 include P21, cyclin B1 (CCNB1), ERBB2, Akt3, SOX4, STAT3, vascular endothelial growth factor A (VEGFA), and Smad7, suggesting that miR-93 may play tumor suppressor roles through diverse mechanisms." (PMID 25649143, 2015). "Importantly, number of genes responsible tumor immune responses and desmoplastic reaction; Mst1r, TGFβr1, TGFβr2, VEGFa, CSF-1, SDF-2, CD44, IL-6ra, PD1, CD68, CD163, fibronection and MMPs were significantly reduced." (PMID 26429877, 2015). "Tumor angiogenesis has been shown to be induced by tumor-derived VEGFA production in zebrafish." (PMID 25768009, 2015). "Evidence is accumulating that activation of the pancreatic endoplasmic reticulum kinase (PERK) in response to endoplasmic reticulum (ER) stress adapts tumor cells to the tumor microenvironment and enhances tumor angiogenesis by inducing vascular endothelial growth factor A (VEGF-A)." (PMID 25794107, 2015). "Similarly, in the older patients, ANGPTL4, MYBL2 and VEGFA, all maintained significance after correcting for subtype and tumor grade in multivariate analysis (Multivariate Model)." (PMID 25999348, 2015). "The LV-miR-497 group displayed reduced AEG-1, CD34 and VEGFA expression in the tumor tissues." (PMID 26336827, 2015). "In addition to the induction of p16INK4a, CDK6 also induces transcription of vascular endothelial growth factor A (VEGFA), a known angiogenic factor and tumor promoter, thereby linking two hallmark cancer features." (PMID 25914884, 2015). "The reduction in VEGFA is also likely to reduce angiogenic responses exploited by tumor cells." (PMID 25794828, 2015). "In addition to the paracrine role in endothelial cells to induce tumor neovascularization, autocrine effects of VEGFA in tumor progression and metastasis have been reported in PCa." (PMID 26019137, 2015). "Vascular endothelial growth factor A (VEGFA) inhibits tumor angiogenesis." (PMID 26045143, 2015). "Efforts to target VEGFA signaling with siRNA and monoclonal antibodies have gained clinical traction, although one can only be cautiously optimistic due to the weak effect on tumor cell survival." (PMID 26089392, 2015). "How S100A4 regulates VEGFA expression in tumor cells, and whether it is directly or indirectly regulated, are interesting questions that remain to be answered." (PMID 25677816, 2015). "Moreover, the potential downstream targets of CXCR7 are VEGFA and galectin-3, which are likely to participate in the regulation of tumor angiogenesis and contribute to the invasiveness of HCC cells." (PMID 25341042, 2014). "Furthermore, miR-503, whose expression is down-regulated by hypoxia through HIF1α, also targets FGF2 and VEGFA for inhibiting tumor angiogenesis and growth." (PMID 24865854, 2014).
tumor (continued). "To obtain further insight into tumor vascularization and VEGFR expression by cancer and non-tumor cells, we used real-time qRT-PCR to quantify species-specific mRNAs of PECAM1/CD31, ENG/CD105, FLT1/VEGFR1, KDR/VEGFR2 and VEGFA genes in a large series of 150 xenografts from different tumor types." (PMID 24625025, 2014). "We evaluated the genes that encode vascular endothelial growth factor A (VEGFA, an isoform of VEGF that is crucial for tumor angiogenesis and plays a key role in endothelial cell proliferation, survival, and permeability), angiopoietin-like 4 (ANGPTL4), and carbonic anhydrase 9 (CA9)." (PMID 24918449, 2014). "Finally, VEGFA levels inversely correlate with miR-26a levels in HCC tumours, and there is also a correlation between miR-26a downregulation and increased angiogenic potential in HCCs." (PMID 25197665, 2014). "CXCR7 expression was further proved to regulate expression of vascular endothelial growth factor A and galectin-3, which may contribute to tumor angiogenesis and invasiveness." (PMID 25341042, 2014). "Also, Mdm2 involvement in promoting tumor angiogenesis and inflammation has recently emerged through its implication in vascular endothelial growth factor-A (VEGF-A) proangiogenic and NF-κB proinflammatory signaling." (PMID 24303114, 2013). "The PI3K-Akt-HIF-1α-VEGFA pathway plays an important role in tumor angiogenesis." (PMID 24194905, 2013). "We speculated that GRN, as an upstream gene protein, might indirectly promote angiogenesis and lymphangiogenesis of tumor by regulating the expression pathway of VEGFA." (PMID 24349832, 2013). "MSC-CM induced expression of VEGFR2 concomitant with high VEGFA expression in SKBR3 cells could generate autocrine loop directly affecting a tumor cell survival and potentially more invasive phenotype." (PMID 24209831, 2013). "VEGFA is the most potent pro-angiogenesis factor, acting directly on endothelial cells to induce endothelial cell proliferation, migration, survival, and finally angiogenesis, which facilitates tumor growth." (PMID 24194905, 2013). "In addition, MR activation attenuates the expression of the VEGF receptor 2/KDR, possibly dampening the activation of a VEGFA/KDR dependent signaling pathway important for the survival of tumor cells under hypoxic conditions." (PMID 23555666, 2013). "miR-15a, miR-16, and miR-503 were reported to inhibit tumor angiogenesis by targeting VEGFA." (PMID 24194905, 2013). "A study in 574 node-negative breast cancer patients showed that high VEGFA levels in tumor tissue were associated with larger tumor size, older age, and negative progesterone receptor (PR)." (PMID 23203097, 2012). "VEGFA levels were significantly higher in all tumor stages vs. the normal tissue." (PMID 22895562, 2012). "For instance, treatment of tumor-bearing mice with VEGFR2-blocking antibodies, sunitinib (Sutent, Pfizer, a multi-targeted receptor tyrosine kinase inhibitor) or genetic deletion of VEGFA shows anti-tumor effects but also triggers local invasiveness and metastasis." (PMID 24213314, 2012). "In addition, mAb bevacizumab blocks tumor angiogenesis by inhibiting vascular endothelial growth factor-A (VEGF-A) expressed by host cells." (PMID 22778760, 2012). "Because vascular endothelial growth factor-A (VEGF) induced angiogenesis plays a critical role in the pathogenesis of cancer, we therefore investigated whether tumor inhibitory effects of THL or its active constituents are through suppression of VEGF actions." (PMID 22937129, 2012). "Moreover, the neutralizing mAb bevacizumab, known to inhibit the proliferation of microvascular endothelial cell line HMEC-1, was used to address the potential role of VEGFA in NRP2-mediated tumor cell growth." (PMID 21747928, 2011). "In this study a model was generated to investigate the effect of VEGFA in tumour progression." (PMID 22045186, 2011).
tumor (continued). "We report here that they are of at least six distinct types, we describe how each forms, and, looking forward, encourage the targeting of tumour vessel subsets that have lost their vascular endothelial growth factor-A (VEGF-A) dependency and so are likely unresponsive to anti-VEGF-A therapies." (PMID 19240721, 2009). "These HPCs and macrophages mobilize in response to growth factors produced by the primary tumor, such as vascular endothelial growth factor A (VEGFA), placental growth factor (PlGF) and transforming growth factor-beta (TGFb), where they establish a pre-metastatic niche." (PMID 19997510, 2009). "In addition, TF is known to contribute to tumour progression indirectly, through the role in haemostasis, and, in part, by upregulating the pro-angiogenic vascular endothelial growth factor-A (VEGF)." (PMID 19623180, 2009). "In this context, SLPI overexpression was associated with increased MMP-9 activity, upregulation of VEGFA and VE-cadherin, and suppression of N-cadherin—molecular features that are characteristic of VM-competent tumor cells rather than endothelial-dependent angiogenesis." (PMID 41557653, 2026). "Next, we asked whether VMP1‐mediated tumor growth was dependent on VEGFA." (PMID 41589276, 2026). "We hypothesize that miRNAs that show significant up- or downregulation in GPs may regulate the expression of genes that are involved in the cell cycle (AURKB, CDC45, and CDK6), cell proliferation (EGFR and VEGFA), and angiogenesis (VEGFA) that support tumor growth." (PMID 40143207, 2025). "For example, collagen deposition induces VEGFA production in tumor cells and promotes angiogenesis and endothelial cell proliferation by upregulating sex-determining region Y-box protein 18, thereby affecting tumor angiogenesis and mediating resistance to pembrolizumab." (PMID 41226585, 2025). "Additionally, in vitro models could test whether VEGFA overexpression drives angiogenesis or tumor cell proliferation." (PMID 40629113, 2025). "In addition, some studies have reported that MEK/ERK signalling pathway may be partially responsible for the accumulation of VEGFA and leads to tumour cell‐mediated angiogenesis." (PMID 40263693, 2025). "In addition, our IF staining showed that increased VEGFA expression led to increased vessel density, accompanied by a reduction in αSMA positive pericyte coverage and a decrease in the level of collagen IV in tumor vessels." (PMID 40860183, 2025). "Furthermore, tumor growth was effectively attenuated in vivo without adverse impacts on body weight, aligning with reduced expression of VEGFA and other malignancy‐associated markers." (PMID 40740483, 2025). "However, subsequent research revealed a more complex effect, showing that anti-VEGFA therapy can also transiently normalize tumor vasculature, improving perfusion through reduced vascular density, increased blood flow, decreased permeability, and enhanced pericyte recruitment." (PMID 40173050, 2025). "Some basic studies on the specific mechanism of visceral fat and tumor have confirmed a positive correlation between visceral adipose tissue and angiogenic biomarkers, particularly with circulating pro-angiogenic biomarker vascular endothelial growth factor A (VEGFA) levels." (PMID 40177184, 2025). "Finally, we examined the spatial distribution of key tumor microenvironment markers such as CD8A, PD-L1, FOXP3, CD163, and VEGFA, further confirming that TMErisk genes aggregate in the tumor center and recruit immune cells, forming an immune hub (Figures 6G1, G2, G3, G4, G5)." (PMID 40104502, 2025).